MIR147A (microRNA 147a)
Synonyms: hsa-mir-147; MIR147; MIRN147; hsa-mir-147a
Gene: MicroRNA gene on chromosome 9 (120,244,979 to 120,245,050, reverse strand). Ensembl gene ENSG00000207814.
Gene Ontology:
Biological process: miRNA-mediated post-transcriptional gene silencing
Cellular component: RISC complex
Diseases named in the same sentence as MIR147A in open-access papers:
MIR147A is named in the same sentence as 2 diseases in open-access papers, as found by Europe PMC text mining. Sharing a sentence is not in itself a finding about the gene and the disease. The quoted sentences say what the papers report.
colitis (1 paper, 2012). Inflammation of the colon. "This possible anti-inflammatory role made Mir147 a candidate colitis gene in Gdac1." (PMID 22970191, 2012).
MIR147A also shares sentences with these, for which no sentence is quoted: periodontitis (1 paper).